DNMT3A (DNA methyltransferase 3 alpha)
Diseases named in the same sentence as DNMT3A in open-access papers (continued):
Sharing a sentence is not in itself a finding about the gene and the disease.
cancer (continued). "Further this study highlights the clinical significance of MTA1, DNMT3a and IGFBP3 in determining an overall poor prognosis of cancer patients." (PMID 28393842, 2017). "Human cancer cells with DNMT1 knockout were found to retain their inherited methylation pattern, suggesting maintenance activity by the expressed DNMT3a and DNMT3b." (PMID 28052028, 2017). "For example, DNMT1 is required for the maintenance of H3K9 methylation in human cancer cells, and DNMT3A PWWP interacts with H3K36me3 and consequently enhances DNMT3A activity." (PMID 28127428, 2017). "UHRF1/2 are frequently overexpressed in cancers and we present evidence that UHRF1/2 overexpression downregulates DNMT3A proteins and consequently leads to DNA hypomethylation." (PMID 27462454, 2016). "For instance, DNMTs (in particular DNMT3A and DNMT3B), which can potentially convert 5hmC to C, are frequently overexpressed in cancer." (PMID 26785262, 2016). "Several human miRs, including miR-29 family, miR-148, and miR-200b/c have been found to be frequently downregulated in human cancers and lead to increase expression of DNMT1 and DNMT3a/b because they directly target the 3′-UTR of DNMTs." (PMID 27384876, 2016). "Existing data has implied that Lsh interacts predominantly with the de novo methyltransferases Dnmt3a and Dnmt3b in MEFs, while this interaction occurs by means of HDAC1 and HDAC2 in transformed cancer cells (HCT116)." (PMID 26491684, 2015). "In cancer biology, TAL-TET1 or TAL fused to DNA methyltransferase DNMT3A (TAL-DNMT3A) was used to manipulate expression of endogenous CRMP4, a suppressor of metastasis." (PMID 26404236, 2015). "DNA-methyltransferase (DNMT)-3A which contains DNMT3A1 and DNMT3A2 isoforms have been suggested to play a crucial role in carcinogenesis and showed aberrant expression in most cancers." (PMID 24667323, 2014). "A regulator of de novo DNMTs, DNMT3a and DNMT3b, DNMT3L promoter was found to have lost DNA methylation to varying levels in 14 out of 15 cancer cervix samples that were analyzed." (PMID 24822169, 2014). "The levels of DNMTs, especially those of DNMT3A and DNMT3B, are often increased in various cancer tissues and cell lines." (PMID 24822169, 2014). "The miRNA-29 family (miRNA-29a,-29b,-29c), which is down-regulated in cancers, was shown to have some interesting complementarity with the 3′UTR of DNA methyltransferase (DNMT)3A and 3B both of which are known de novo methyltransferases." (PMID 23497588, 2013). "In a variety of cancers, DNMT1, DNMT3a, and DNMT3b were reported to be highly expressed and associated with poor prognosis." (PMID 22768205, 2012). "MicroRNA-29b has been shown to target and knock down expression of both DNMT3A and DNMT3B in cancer cells, with a consequent decrease in genome-wide methylation." (PMID 21712824, 2011). "Aberrant CpG-island methylation in cancer is regulated by DNMT1, DNMT3A and DNMT3B which catalyze the transfer of a methyl moiety from the methyl donor S-adenosyl-L-methionine to the carbon-5 of a cytosine base." (PMID 21629434, 2010). "We found that the expression of SPIN4, EZH2, and DNMT3A to be elevated in many human cancers compared to the corresponding non-malignant tissue samples." (PMID 41676612, 2026). "Finally, the active DNA demethylation activity of DNMT3A has now emerged as a new potential target for therapeutic development to prevent EMT and metastasis of cancer cells." (PMID 40764968, 2025). "The genes revealed by RNA-seq to be tightly regulated by DNMT3A in HEK293T cells in this study are of great significance to understanding the functions of DNMT3A in the origin and development of tumors and are potential novel targets for future cancer therapy." (PMID 41450820, 2025).
cancer (continued). "By analyzing the expression patterns of these DNA methylation writers and erasers, we observed that the most notable alterations in cancers were elevated levels of DNMT1, DNMT3A, and DNMT3B, which is consistent with the previous result of global DNA hypermethylation in a broad array of cancers." (PMID 38666956, 2024). "Overexpression of DNMTs (e.g., DNMT1, DNMT3A and DNMT3B) could promote DNA hypermethylation, which was closely related to the prognosis in cancer patients (Weisenberger, Lakshminarasimhan & Liang, 2022)." (PMID 38766487, 2024). "Lastly, we have carried out our experiments in human cancer cells, but it will be worthwhile in the future to clarify whether UHRF1 also promotes DNMT3A/DNMT3B activity in other systems, such as mouse embryonic stem cells." (PMID 38580649, 2024). "This was the first study to show that DNMT3A and TET2 methylation levels change with the degree of cancer differentiation and that DNMT3A knockdown or TET2 overexpression could effectively inhibit the proliferation and migration of OSCC." (PMID 38246976, 2024). "For each gene, the correlation between its mRNA expression level and genomewide LPMD or DNA methylation level were computed across the cancer cell lines, and we observed moderate negative correlation between DNMT3A expression and LPMD levels." (PMID 36940213, 2023). "Additionally, we explored the correlation between IL18RAP and five methyltransferases (DNMT3L, DNMT3B, DNMT3A, TRDMT1, and DNMT1) across cancers." (PMID 37698530, 2023). "In addition, FEN1 can modify the epigenetic features in cancer cells by inducing the upregulation of DNA methyltransferase 1 (DNMT1) and DNMT3a and interacting with DNMT3a through proliferating cell nuclear antigen (PCNA)." (PMID 36672839, 2022). "In addition, OAS3 was positively correlated with four major DNA methyltransferases including DNMT1, DNMT2, DNMT3A, and DNMT3B in most cancer types." (PMID 35592250, 2022). "The combination of Cur and decitabine showed a different mechanism of action based on inhibiting the formation and migration of cancer cell colonies, the total activity of DNMT and the expression of the DNMT3a, these combination were also showed in other natural epidrugs." (PMID 35327559, 2022). "This hypothesis is borne out by previous studies demonstrating that DNMT3A/3B cooperate in OCT-3/4 and NANOG promotor methylation during the differentiation of embryonic stem cells and carcinoma cells." (PMID 35081981, 2022). "Collectively, the DNMT3A, DNMT3B, DNMT1, and ALYREF might function as poor prognosis predictors in cancer progression." (PMID 34325709, 2021). "Previous studies have clarified that miR‐101‐3p regulates various pivotal oncogenes and that downregulation of this miRNA affects cancer cell proliferation, metastasis, drug resistance, and angiogenesis via targeting of several oncogenic targets, e.g. EZH2, STMN1, VHL, SOX2, and DNMT3A." (PMID 31755218, 2020). "Therefore, we investigated the effect of mutations on DNA methylation modification genes such as DNMT1, DNMT3A, MBD1, MBD4, TET1, TET2 and TET3 through a pan-cancer analysis." (PMID 32093698, 2020). "Interestingly, BRAP expression was strongly correlated with DNMT1, DNMT2, DNMT3A, and DNMT3B expression in human pan-cancer, and UCS, TGCT, and SARC were exceptions." (PMID 33240929, 2020). "We observed that DNA methyltransferase genes such as DNMT1, DNMT3A, and DNMT3B were overrepresented in all cancer groups, with a significant difference between the SH and SL samples in both ADCs and SCCs, which prompted us to explore the genome for the methylation states." (PMID 33343623, 2020).
cancer (continued). "For DNMT3A, 2i treatment affected neither the levels of protein nor mRNA in majority of the cell lines, although a few of cancer cells showed increased levels of transcription." (PMID 30696879, 2019). "We found that 2i broadly down-regulated both UHRF1 and DNMT1, the axis of DNA maintenance methylation, but not de novo enzyme DNMT3A, in various cancer cells." (PMID 30696879, 2019). "In cancer tissues, DNMT3B is expressed more frequently compared to DNMT1 and DNMT3A." (PMID 29796115, 2018). "Moreover, RRx-001 significantly decreased DNMT1 and DNMT3A protein expression in a dose- and time-dependent manner in murine SCC VII cancer cells and induced demethylation of genes important in pathways relevant to cancer." (PMID 28149332, 2017). "Overall, results presented here show that the high levels of IGFBP3, low levels of DNMT3a, and high levels of MTA1 may result in poor prognosis of cancer patients and that the expression of IGFBP3 by MTA1 could be regulated by direct or indirect mechanisms." (PMID 28393842, 2017). "Hematopoietic stem cells (HSCs) lacking Dnmt3a cannot differentiate correctly upon serial transplantation, and end up developing a range of severe myeloid and lymphoid malignancies in aged animals." (PMID 28425913, 2017). "mRNA expression of DNMT1, DNMT3A, DNMT3B, and six different isoforms of DNMT3B were examined by real-time PCR, with only DNMT3B4 exhibiting significantly different expression levels between cancer tissues and adjacent normal tissues." (PMID 28160561, 2017). "In this regard, it is not a coincidence that DNMT3A is shown to play a key role in maintaining methylation in repetitive sequences and DNA hypomethylation in cancer is generally observed in highly repetitive sequences." (PMID 27462454, 2016). "Having established that both UHRF1 and UHRF2 target DNMT3A for degradation and that downregulation of DNMT3A correlates with DNA hypomethylation, we next investigated the expression profiles of UHRF1 and UHRF2 in various cancers." (PMID 27462454, 2016). "It is noteworthy that the RNA-seq data indicate that both DNMT1 and DNMT3A are also overexpressed in most if not all cancers, consistent with previous observation for coordinated overexpression of DNMT3A, DNMT3B and DNMT1 in cancers." (PMID 27462454, 2016). "Also in agreement with the observed widespread overexpression of UHRF1 in cancers, our data suggest that UHRF1 is likely to have a broader role in negative regulation of DNMT3A than UHRF2." (PMID 27462454, 2016). "Although UHRF2 is less frequently overexpressed in cancers in comparison with UHRF1 and is therefore less responsible for downregulation of DNMT3A in cancers, in a few cancer cell lines, especially A549, UHRF2 appears to play a dominant role in negative regulation of DNMT3A." (PMID 27462454, 2016). "In particular, DNMT3A, one of the putative BRAFV600E targets, may reprogram epigenetic modifications to facilitate cancer development." (PMID 25890285, 2015). "With the exceptions of DNMT3B, which is significantly overexpressed in most cancer types studied here, and DNMT3A which is highly mutated in LAML, we do not see notable mutation rates or cancer-associated changes in expression level for DNMTs and HDACs." (PMID 25484917, 2014). "When using SNVs only, most such genes were known cancer genes, such as U2AF1, IDH1, and DNMT3A in LAML (FLT3 SNVs cluster within five amino acids), AKT1 and KRAS in BRCA, BRAF and KRAS in COADREAD, IDH1 and PARG (poly (ADP-ribose) glycohydrolase) in GBM, and KRAS in UCEC." (PMID 25348067, 2014). "Immunoreactivity for DNMT3A was detected in the cytoplasm but not in the cell membranes of cancer cells." (PMID 20128888, 2010). "This suggests that variations in PTEN and DNMT3A expression may influence how long a patient lives with cancer without the disease worsening after treatment." (PMID 40649942, 2025).
cancer (continued). "In addition, we analyzed the correlation between PGAM1 and methylation-related genes, and the results showed that PGAM1 had significant correlations with methyltransferases such as DNMT1, DNMT3A and DNMT3B as well as methylation modifications such as m1A, m5C and m6A across various cancers." (PMID 38434965, 2024). "LINC00922 binds to DNMT1, DNMT3A, and DNMT3B and is enriched in the promoter region of the downstream tumor suppressor NKD2, thereby inhibiting its expression through methylation, which ultimately activates the Wnt signaling pathway and promotes cancer progression." (PMID 37901333, 2023). "Results showed that the autoantibodies against DNMT3A and HSP60 showed higher expression in the LC group compared to the HCC, one possible reason could be that most of the LC patients retained the pre-cancer status and were prone to generate greater anti-TAA immune reactivities." (PMID 36291095, 2022). "Moreover, 3-MA, a PI3K inhibitor could reduce the activation of PI3K/Akt signaling pathway and reverse the DNMT3a and 3b levels in AGS and SW480 cancer cell media treated cardiomyocytes." (PMID 35265687, 2022). "Furthermore, after using 3-Methyladenine (3-MA), an inhibitor of PI3K, the increased levels of phosphorylated PI3K and Akt were decreased, and DNMT3A, DNMT3B, KCND3, and KCNQ1 levels were also rescued compared with AGS and SW480 cancer cell media treated cardiomyocytes." (PMID 35265687, 2022). "Of particular interest were the hypermethylation of DNMT3A, a DNA methylation writer, in five cancer types and TET2, a DNA methylation eraser, in four cancer types, suggesting a possible mechanism in which global DNA methylation changes may be effected via hypermethylation of these targets." (PMID 34871444, 2021). "In light of the prevalent and conserved roles of EZH2, DNMT3a, lncRNAs, and miRNAs in epigenetic regulation, the potential implications of the SChLAP1/EZH2/miRNA axis and the feedback loop between miRNAs and DNMTs in other human cancers also deserve further explorations." (PMID 33589600, 2021). "In addition, a Boolean model derived from a smaller network-module representing the crosstalk between FLT3, DNMT3A, NPM1 and cancer hallmarks, when primed with patient-specific genomic profiles, yielded predictions that are in accord with patients’ clinical data." (PMID 33578936, 2021). "Therefore, our preclinical data provide a promise to selectively treat cancer patients whose tumors carry deleterious TET2 and nonsynonymous DNMT3A mutations." (PMID 34039392, 2021). "However, it is widely known that the levels of DNMTs, (DNMT3B, DNMT3A, and DNMT3L) are often increased in various cancer tissues and cell lines, and may account for the hypermethylation of tumor suppressor genes in a variety of malignancies." (PMID 34063128, 2021). "Current research is also exploring the possible development of DNMT3a inhibitors, which could provide new insights into AML development and offer a preventative treatment strategy for patients suffering from MDS and other hematological pre-cancers." (PMID 34358067, 2021). "Interestingly, another study indicates an opposite effect that NF-κB/p65/MUC1-C complex occupy the promoters of DNMT1 and DNMT3B to drive their transcription, but not DNMT3A in carcinoma cells." (PMID 34482802, 2021). "Indeed, considering that DNMT3A is involved in de novo DNA methylation, an increase of UHRF1 through the targeting of DNMT3A also likely contributes to the global DNA hypomethylation in cancer cells." (PMID 30669400, 2019). "Thus, the overexpression of DNMT3B, but not DNMT1 or DNMT3A, has been observed in several types of cancers, and suggests an important role for DNMT3B in tumorigenesis." (PMID 28160561, 2017).
cancer (continued). "Mirza and colleagues reported decreases in the transcript levels of DNMT1, DNMT3A and DNMT3B with the incorporation of WA, and use their findings to suggest that WA may have beneficial therapeutic effects against cancer through its ability to reverse changes in the epigenome." (PMID 28534825, 2017). "MUC1-C induces the expression of DNMT1 and DNMT3b, but not DNMT3a, in carcinoma cells." (PMID 28785086, 2017). "Thus, the destabilization and mis-targeting reported in their study may operate under excessive UHRF1 overexpression, as they suggested, whereas the negative regulation of DNMT3A by UHRF1/2 reported in our study occurs in both regular and cancer cells." (PMID 27462454, 2016). "However, whether DNMT3A acts as OG or TSG has been debated, and additional studies are required to understand the exact role of DNMT3A in cancer." (PMID 26110843, 2015). "However, results showed that both of DNMT1 and DNMT3a were not significantly changed by TQ treatment in the tested cancer cell lines." (PMID 26023736, 2015). "As compared to normal CD138+ cells,PCs from MM and PCL patients showed higher expression of DNMT3A, and, at a lesser extent, of DNMT3B mRNAs, suggesting a potential role of de novo DNMTs in malignanttransformation; conversely, DNMT1 levels were lower in cancer cells compared to normal PCs." (PMID 23100393, 2012). "In addition, over-expression of DNMT3b, but not DNMT1 and DNMT3a, is common in various cancer cells, suggesting that DNMT3b plays an important role in the development of aberrant promoter methylation during oncogenesis." (PMID 17938735, 2007). "In this study, we found global hypomethylation and increased concentrations of plasma DNA methyltransferases (DNMT1, DNMT3A, and DNMT3B) among cigarette smokers in Saudi compared with non-smokers, which may reflect the molecular mechanisms linking smoking and diseases, such as cancer." (PMID 40003580, 2025). "However, the mechanistic basis for the fundamental roles of DNMT3A and DNMT3B in tumorigeneses and cancer progression remains largely unknown, and it therefore becomes important to understand the underlying mechanism determining their occupancies on chromosomes and their distinct functions." (PMID 37072414, 2023). "Although the DNMT3a protein levels appears to be elevated in cancer tissues as compared with the adjacent normal colon tissues as well, the image quality of immunoblotting results appears low, probably due to low abundance and degradation of DNMT3a in the tissues (data not shown)." (PMID 34268315, 2021). "Indeed, de novo methylation of genes frequently observed in cancers could be catalyzed by DNMT1 rather than DNMT3A or DNMT3B." (PMID 29449903, 2018). "The reasons for cancer-specific patterns evolving in the absence of Dnmt3a remains unclear." (PMID 27677595, 2016). "In cell-based and in vivo cancer models, only DNMT3B enzymatic activity, and not DNMT1 or DNMT3A, affects Ccnd2 expression." (PMID 36739439, 2023). "Conversely, in patients with non-DDR CHIP (i.e., DNMT3A), the clones outcompeted the DDR CHIP lesions if the patients was not subsequently exposed to any cancer treatment." (PMID 33562056, 2021). "Unexpectedly, the expression of LEPROT was positively correlated with that of DNMT1 and DNMT3A but not DNMT3B in most cancers and was consistently positive-correlated with DNMT2 in all cancers." (PMID 34804118, 2021). "Nevertheless, as already observed in different cancer cell lines after SGI-1027 and MC3343 treatment, also the novel MC3353 provided protein degradation of DNMT3A, the enzyme mainly inhibited." (PMID 31060628, 2019). "In this context, recent studies in human carcinoma cells have shown that MUC1-C drives transcription of DNMT1 and DNMT3b, but not DNMT3a." (PMID 27259275, 2016). "Similarly, the DNMT1, DNMT3A and DNMT3L protein levels were overexpressed and DNMT2 expression was reduced in high-grade carcinomas compared to non-neoplastic tissue and low-grade tumors." (PMID 37894317, 2023).
cancer (continued). "Indeed, the de novo methylation of genes frequently observed in cancers could be catalyzed by DNMT1, rather than by DNMT3A or DNMT3B." (PMID 30669400, 2019).